NF1 (neurofibromin 1)
Diseases named in the same sentence as NF1 in open-access papers (continued):
Sharing a sentence is not in itself a finding about the gene and the disease.
tumor (continued). "Better understanding of MPNST variable occurrence in NF1 has been elusive, due to the tumor's low frequency and the uncommon presentation in multiple members of the same family." (PMID 20687928, 2010). "Completing this mutation analysis would have greatly enhanced our understanding of the unusual co-existence of this tumour in the setting of a non-NF-1 patient, and, also shed more light on its unusual pattern of recurrence." (PMID 19216788, 2009). "There were alsosignificant differences in the distribution of the site of tumours between thetwo groups with relative overrepresentation of peripheral limb tumours in the sporadicgroup and axial tumours in the NF1 group (X2 = 24.3, P < .001)." (PMID 19360115, 2009). "Tumour volumewas the only other factor that, together with NF1, remained significant onmultivariate analysis." (PMID 19360115, 2009). "Peripheral lower limb tumours accounted for the greatestproportion of tumours from the NF1 group (32%) and formed the majority (58%) oflarge volume tumours." (PMID 19360115, 2009). "The NF1 gene functions as a tumor suppressor, but haploinsuffiency probably accounts for some aspects of the non-tumor phenotype." (PMID 18671845, 2008). "The NF1 gene is considered a tumor suppressor gene and inactivation of both copies can be found in NF1-associated benign and malignant tumors." (PMID 16961930, 2006). "The majority of the cell lines contain the NF1 two-hit tumor cells." (PMID 41564118, 2026). "NF1-mutant tumors did not exhibit increased global tumor mutational burden or uniform APOBEC hypermutation but showed distinct single-nucleotide substitution patterns and frequent comutations in core DDR-related genes." (PMID 42158468, 2026). "A significant challenge has been the lack of appropriate control cell lines needed to distinguish candidate therapies that selectively target NF1-deficient tumor cells without causing general cytotoxicity." (PMID 41294711, 2025). "Furthermore, there was a significant reduction in tumor cell growth in CQ‐treated mice in comparison to selumetinib‐treated mice, indicating CQ to have a superior effect on NF1‐mutant tumor growth." (PMID 39129390, 2025). "In contrast, despite Nf1Indel alone being more potent tumor inducer than Pik3caH1047R by itself, no discernible gene group emerged across the models that harbor a Nf1 loss of function mutation." (PMID 41000773, 2025). "However, in non-NF-1 OPGs, there was a minor, thus significant correlation between tumor volume at diagnosis and logMAR values of WSE (R2 = 0.37, p = 0.02)." (PMID 40643687, 2025). "Historically, tumor development has been the most studied aspect of the NF1 clinical problems." (PMID 40812791, 2025). "Germline NF1 loss and somatic NF1 alterations result in RAS/MAPK pathway hyperactivation, a central driver of cell proliferation and genomic instability that is implicated across multiple tumour types." (PMID 41245174, 2025). "In some mouse models of NF1, a heterozygous environment can increase tumor size." (PMID 40992926, 2025). "Successful treatment of pNFs might alleviate these symptoms along with potentially reducing the risk of malignant transformation into the most aggressive and deadly NF1-related tumor, MPNSTs." (PMID 41294711, 2025). "These mutations lead to MAPK pathway hyperactivation and are strongly correlated with a high tumor mutational burden (TMB), which may enhance responsiveness to immune checkpoint inhibitors, though targeted therapies remain limited for NF1-mutant disease." (PMID 40984902, 2025). "Patients with NF-1 at a younger age and larger tumours tend to undergo malignant transformation." (PMID 40230769, 2025). "All three NF1-LOF tumor cell lines were insensitive to vemurafenib." (PMID 40111124, 2025).
tumor (continued). "In addition to providing in vivo NF1 tumor models for preclinical testing, cell lines have been established from several of these GEMMs, which have been useful in HTS." (PMID 41294711, 2025). "We then performed DE analysis to compare Nf1flox/+ versus Nf1 +/+ tumors within tumor types." (PMID 39804140, 2025). "A two-year-old patient with a history of neurofibromatosis type 1 (NF1), NF1 microdeletion and variants of uncertain significance in the CASR, NF2, and POLD1 genes, presented with intestinal subocclusion caused by a 15 cm heterogeneous pelvic tumor." (PMID 40630346, 2025). "It is caused by germline mutation in the NF1 gene, a tumor suppressor gene that encodes neurofibromin, a negative regulator of intracellular RAS/MAPK signaling." (PMID 40000831, 2025). "In light of the unresolved challenges and the pressing need for an effective therapeutic strategy targeting the tumor immunosuppressive network, we have developed an intervention approach by tailoring a tumor cell‐derived GA‐targeting self‐assembled peptide (NF‐1)." (PMID 39908165, 2025). "An important question is whether MAP2K1-driven tumours align with conventional WHO melanomagenesis pathways, alongside BRAF, NRAS, and NF1 mutations, or pathway IV (Spitz), alongside kinase gene fusions and HRAS mutations." (PMID 40107205, 2025). "Overall, these data showed a bell-shaped curve of pERK modulation in response to tovorafenib, TAK-632, LXH254, BGB-283, and belvarafenib in NF1-LOF mutant tumor cell lines, suggesting that this may potentially be a class effect." (PMID 40111124, 2025). "Consequently, researchers use Cre-LoxP technology to conditionally knock out (KO) Nf1 in specific cell types to initiate tumor formation." (PMID 41294711, 2025). "This ultimately leads to the development of a variety of benign and malignant tumours seen in NF1." (PMID 39254838, 2025). "While mTOR inhibition did not lead to reductions in pNF tumor volume, patients with NF1-associated LGGs experienced either tumor shrinkage or stabilization, with minimal side effects." (PMID 41294711, 2025). "Lastly, we unexpectedly discovered that GNAQQ209L expression in Plp1-expressing cells can drive the formation of neoplasms similar to cutaneous neurofibromas even without Nf1 loss." (PMID 39804140, 2025). "Similarly, tumor surveillance guidelines for individuals with NF1 issued by the European Reference Network on Genetic Tumor Risk Syndromes (ERN GENTURIS) state that GIST surveillance should be performed based on the clinical suspicion of symptoms." (PMID 40247846, 2025). "Currently, predictive biomarkers for treatment response are lacking, but assessment of NF1 mutation status, pathway activation profiles, and liquid biopsy approaches like circulating tumor DNA (ctDNA) hold promise for guiding therapy." (PMID 41294711, 2025). "UMAP analysis revealed a total of 22 cell clusters comprising 10 tumor cell clusters and 12 nontumor cell clusters that were generally conserved based on NF1 mutation status or sample of origin." (PMID 40985888, 2025). "Loss of NF1 results in a hyperactive RAS signaling pathway and its downstream cascades, including the MAPK pathway (RAF/MEK/ERK), which promotes abnormal cell proliferation and neoplasia." (PMID 40563570, 2025). "In addition to tumor development, NF1 has a wide variety of clinical manifestations including café au lait spots, Lisch nodules, cardiovascular abnormalities, skeletal defects, and cognitive and behavioral difficulties." (PMID 40812791, 2025). "Intriguingly, enhancing MET expression in murine Schwann cells that also lack Nf1 drove tumorigenesis, whereas the loss of Nf1 alone generally did not induce tumor formation." (PMID 40723291, 2025). "Tumor burden showed significant correlation with VA impairment at diagnosis and individual logMAR change during follow-up (R2 = .22, p = .011), while individual tumor growth velocity during follow-up showed correlation with VA deterioration in non-NF1 OPG (R2 = .35, p = .04)." (PMID 40643687, 2025).
tumor (continued). "The bell-shaped pERK modulation in NF1-LOF tumor cell lines seems to be a class effect." (PMID 40111124, 2025). "Furthermore, CQ treatment also significantly reduced tumor growth in a xenograft NF1 mouse model, outperforming selumetinib." (PMID 41294711, 2025). "Secondly, known risk factors associated with relapse for sporadic GISTs (size, mitotic count, location, tumor rupture, mutation) have never been studied in the NF1-GIST subpopulation." (PMID 40043354, 2025). "Similarly, NCT03871257 evaluates selumetinib vs. CV for treating LGG for patients with NF–1, focusing on tumor control and its potential to improve vision for those patients with OPG." (PMID 40867225, 2025). "We previously demonstrated that murine Nf1-OPG growth is tightly regulated by neuron-immune-tumor interactions, such that Nf1-mutant neurons, specifically retinal ganglion cells (RGCs), induce T cell-TAM stromal support through the expression of midkine (Mdk), a secreted growth factor." (PMID 41497446, 2025). "Similar to other tumor suppressor genes, NF1 inactivation typically follows a biallelic “two-hit” model, where individuals inherit a germline mutation in one allele and acquire a somatic mutation in the second allele during early development or later in life, leading to localized tumor formation." (PMID 41374990, 2025). "Future work could include germline NF1 testing, tumor sequencing, and methylation-based subgrouping to clarify the genetic basis of this association." (PMID 41216086, 2025). "This alternative splicing event is relevant when NF1 symptoms are caused by NF1 haploinsufficiency such as learning and behavioral defects but not in tumor development when both alleles of NF1 are null." (PMID 40812791, 2025). "The NF1 tumor types that have received the most attention by researchers are pNFs and MPNSTs." (PMID 41294711, 2025). "The NF1::SCAMP5 fusion may disrupt the NF1 tumor–suppressor function while activating SCAMP5-mediated oncogenic pathways, driving myeloid proliferation." (PMID 40761243, 2025). "Previous studies have primarily examined the independent tumor-suppressive functions of NF1 or SPRED2 in various cancers; however, the cooperative interaction between these proteins and their biological significance in BC remain unclear." (PMID 41155378, 2025). "The tumor microenvironment also plays a crucial role, with differences in immune cell populations noted in NF1 heterozygous conditions that may enhance tumor growth." (PMID 40182390, 2025). "Because homozygous NF1 mutant mice do not survive, traditional NF1 animal models are heterozygous, but the tumor tissues of these heterozygous mice show the loss of wild-type NF1 gene." (PMID 40895107, 2025). "Given this and our ability to detect tumor contamination accurately, the NF1 mutations in normal tissues are not the result of tumor cells infiltrating normal tissues." (PMID 40000831, 2025). "Loss of NF1 function leads to persistent RAS activation and promotes tumor growth." (PMID 41374990, 2025). "While NF1 and CBL mutations may contribute to tumor initiation in EOCRC, BRAF-driven signaling appears to play a more prominent role in LOCRC." (PMID 40282501, 2025). "Many type II RAF inhibitors, including tovorafenib, potently inhibit wild-type and altered BRAF and CRAF but are ARAF sparing, which may explain the pattern of pERK modulation observed in the NF1-LOF tumor cell lines treated with these agents." (PMID 40111124, 2025). "However, the remaining CpG sites investigated were unmethylated across all of the other tissue samples studied, including both the NF1-related tumour samples and the peripheral blood leukocytes from the NF1 patients and healthy controls." (PMID 40843672, 2025).
tumor (continued). "Type-1 and type-2 deletions at the NF1 locus constitutively result in ATAD5 haploinsufficiency, which most probably constitutes an additional risk factor for genomic instability and tumour emergence." (PMID 38448973, 2024). "We found no significant change in the association of NF1 as a poor prognostic indicator of mortality with time of publication or with the anatomical location of the tumor." (PMID 38191386, 2024). "The difference in tumor initiation between the Nf1 indels offers distinct models in which to study the pretumorigenic changes, with a long window of before tumor onset in IF/+ rats compared to the rapid tumor onset that occurs in the PS-20/+ and IF; PS-21/+ lines." (PMID 38799507, 2024). "Additionally, based on our systematic review, we recommend the inclusion of MRI and FDG PET/CT scans for the assessment of tumour burden and detection of MPNSTs, respectively, for adult NF1 surveillance." (PMID 38539455, 2024). "In one of these cases, other mutations such as PPM1D and NF1, which were identified in the tumor tissue samples, were also not detected in the CSF samples." (PMID 38388726, 2024). "However, NF1 studies, including the current study, mainly used Schwann cells because they are considered the main cell type of tumor origin." (PMID 39273214, 2024). "Moreover, the tumor suppressors ARID1B, CDKN2A and NF1 were commonly affected by chromosomal copy loss." (PMID 38191367, 2024). "Furthermore, molecular profiling of human NF1-associated LGG revealed a subgroup of tumors with enrichments in immune-related transcripts, increased T cell infiltration, and abundant tumor neoantigens." (PMID 38473354, 2024). "Thus, inhibitors of SHP2 can block the RTK/RAS/MAPK signaling pathways and inhibit the growth and proliferation of tumor cells driven by RTK or with KRAS, BRAF Class 3 and NF1 loss of function mutations." (PMID 39184861, 2024). "Moreover, NF1 is associated with an 8–13% lifetime risk of developing MPNST, which are aggressive tumours that metastasise widely and have a poor prognosis." (PMID 38893021, 2024). "NF1, TSC1, and TβRII deficiency in TSAE1 tumor cells significantly increased lung nodule counts." (PMID 38997291, 2024). "In the other 10 NF1-associated cases, there were no typical conventional MRI criteria suggestive of malignancy (rapid tumor growth, large lesions, or the inhomogeneous signal intensity “target sign” in the MRI)." (PMID 39594712, 2024). "Partly due to physiological adrenal uptake of 68Ga-DOTA-SSA PET/CT, more tumor specific 18F-FDOPA PET/CT may be preferred in PCCs that are small and/or related to known mutations in NF1, RET, VHL, or MAX." (PMID 38206185, 2024). "The appearance of a tumour with an unfavourable location, its growth rate specific to NF1 and the impossibility of radical resection in surgical treatment may even constitute a source of serious disability for the sick individual." (PMID 39536012, 2024). "NF1 is a tumor suppressor gene that helps regulate cell division and prevent tumor formation." (PMID 38418494, 2024). "Malignant peripheral nerve sheath tumors may be difficult to diagnose as other tumor entities can mimic their morphology and marker expression patterns, especially outside the NF1 clinical context." (PMID 37798904, 2024). "Thus, loss of genes encoding NF1, TSC1, or TβRII resulted in tumor cell-autonomous inflammatory reprogramming through the activation of the JAK-STAT3/6 pathway and resulted in increased production of IL6 and IDO1." (PMID 38997291, 2024). "With consistent epidemiologic data, these changes may be attributed to the growing acceptance of comprehensive treatment algorithms respecting age, tumor‐site, and NF1 status." (PMID 38923198, 2024).
tumor (continued). "Moreover, whereas NF1 hypermutation is related to CD8+ T cell enrichment, loss of NF1 in MES GBs increases the tumor-associated macrophages/microglia infiltration; accordingly, M2 macrophages detection is associated with rapid relapse after radiation therapy." (PMID 38391963, 2024). "Additionally, miR-27a and miR-27b are highly expressed in MPNST and contribute to its malignant behavior by directly targeting the NF1 gene, which is a key tumor suppressor." (PMID 39594601, 2024). "A recent retrospective review of the AACR genie, a clinico-genomic database showed that co-occurring MAPK-pathway mutations (e.g., NRAS, NF1) are significantly more likely with class-1 MAP2K1-mutations (82.3%) compared to class-2 (30.9%) and class-3 (10.6%) in any tumor type." (PMID 39314226, 2024). "Three LGG patients were IDH—wildtype; one patient carried TRIM33–NTRK2 fusion; two other patients had genotypes more specific for HGG tumor types (CDKN2A deletion, PTEN mutation, and PTEN deletion in one case and TERTp mutation, PTEN mutation, and NF1 mutation in another)." (PMID 39684714, 2024). "It paralleled the evolution of comprehensive treatment algorithms; thus, it may reflect alignment of surgical practice to recommendations in respect to age, tumor site, and NF1‐status integrated as such into current treatment guidelines." (PMID 38923198, 2024). "Therefore, in this study, we aimed to elucidate the detailed genetic and clinical characteristics of NF1 in a hereditary tumor cohort." (PMID 39592598, 2024). "Despite best efforts in treatment of NF1, the clinical course of the disease is often characterized by recurrence, as unrecognized tumor tissue may lead to progression of the lesion." (PMID 38603731, 2024). "Additional driver mutations have been found to involve the neurofibromin 1 (NF1) and the KIT (1–2%) genes, while mutations associated with tumor development have been observed in the cyclin-dependent kinase inhibitor 2A (CDKN2A) gene, a well-known cell cycle regulator." (PMID 39199632, 2024). "NF1 immunostaining results were evaluated for each tumor in the context of NF1 genomic status." (PMID 39472976, 2024). "Genetically engineered mouse models (GEMMs) of pNFs and MPNSTs utilize promoters of neural crest or early Schwann cell progenitor genes, such as Krox20, Hoxb7, Dhh, and Prss56, and provide solid support of NF1 tumor initiation and demonstrate their neural crest origin." (PMID 39518076, 2024). "Previously identified CSC markers can be the key to NF1 tumor pathogenesis and therapeutic targets." (PMID 39518076, 2024). "NF1 encodes a GTPase-activating protein that negatively regulates Ras pathway activity by accelerating the hydrolysis of Ras-bound GTP, thereby acting as a tumor suppressor." (PMID 39461475, 2024). "Loss of function mutations in NF1 lead to sustained activation of intracellular RAS-GTP, prolonged activation of the RAS/RAF/MAPK signaling pathway, uncontrolled cell proliferation, malignancy, and tumor growth." (PMID 37147639, 2023). "To further confirm the predictive performance of the IRRS, we also compared the C-index values for the IRRS with those for tumor stage, tumor mutation burden (TMB), and driver mutations (BRAF, NF1, and RAS); the results showed that the IRRS had the best predictive effect with respect to prognosis." (PMID 36875110, 2023). "Our results failed to support the hypothesis that high perigestational folic acid intake in a model of NF1-affected mice increases the rate or severity plexiform-like tumor formation in offspring." (PMID 37848948, 2023). "Both classifications exclude JMML from the category of overlap neoplasms, since JMML is a pediatric-onset entity with germline predisposition, typically characterized by the presence of germline PTPN11, CBL, and NF1 mutations and by predominantly myeloproliferative features." (PMID 37370785, 2023).